HSF1 (heat shock transcription factor 1)
Diseases named in the same sentence as HSF1 in open-access papers (continued):
Sharing a sentence is not in itself a finding about the gene and the disease.
cancer (continued). "HSF1 is highly expressed in some types of solid cancers and may be used as a new biomarker to evaluate prognosis of cancer patients." (PMID 30326922, 2018). "Furthermore, cancer cells can up-regulate HSF1 activity in non-cancer cells within the tumour microenvironment to promote the expression of proliferative and metastatic factors." (PMID 30111611, 2018). "The use of different approaches to inhibit HSF-1, alone or in combination with other target proteins, in vitro and in small animal models have shown promising results in increasing drug sensitivity and avoiding cancer relapse." (PMID 29682483, 2018). "The tumorigenic property of HSF1 stems from activation of distinct transcriptional programs, including oncogenic support processes such as cell-cycle regulation, metabolism, adhesion, and translation, in both cancer cells and the tumor stroma." (PMID 30131848, 2018). "The cancer bioinformatics approach taken by us provides new information about the overexpression of HSF1-CanSig 8q genes mediated by HSF1 in different tumor types, illuminating the connection between malignancy progression driven by HSF1 and pre-mRNA 3′ processing." (PMID 29268782, 2017). "The mechanism by which HSF1 is precisely regulated in cancer remains to be fully elucidated." (PMID 28783244, 2017). "In addition, there is increasing evidence indicating that HSF1 is involved in the cancer stem cell (CSC)-like phenotype." (PMID 28241425, 2017). "The requirement for HSF1 for the cancer development has been well documented." (PMID 28914774, 2017). "Since then, investigation has intensified into the possible roles HSF1 has in cancer and to which cancer types HSF1 may be relevant." (PMID 29088759, 2017). "The role of HSF1 played in cancer proliferation and malignancy is critical and well established." (PMID 29268782, 2017). "We next investigated whether AKT and HSF1 are activated in mammospheres, an in vitro model that enriches the cancer stem cell population." (PMID 29088759, 2017). "Additionally, this study highlights the connection between cellular processes triggered by HSF1 and pre-mRNA 3′ processing in cancers." (PMID 29268782, 2017). "In contrast, HSF-1 is constitutively active in cancer cells and plays a multifaceted role in carcinogenesis, including expression of atypical levels of Hsps, malignant transformation, and others, hence identified as a biomarker for cancer prognosis." (PMID 29348836, 2017). "This set of genes is known as the HSF1 Cancer Signature genes or simply HSF1-CanSig genes." (PMID 29268782, 2017). "However, in the previous study, HSF1 has been proved to lead to a high degree of malignant tumor and promote tumor growth." (PMID 28430589, 2017). "In cancer cells, HSF1 could drive a transcriptional program that is vital for supporting the malignant state of cancer, and the transcriptional program was highly enriched in protein translation, RNA binding, metabolism, and cell adhesion." (PMID 28783244, 2017). "Our finding that SF3B1 can regulate HSF1 concentration could have profound implications for cancer biology." (PMID 28445500, 2017). "This issue is not necessarily unsurmountable, however, as it has also been shown that the HSF1 drives a different transcriptional program and stimulates different sets of cellular processes in cancer cells (including proliferation, invasion, and metastasis) than it does in normal cells." (PMID 28293421, 2017). "Since it has been noted that downregulation of HSF activity sensitizes cancer cells to anticancer drugs, anti-HSF1 aptamers could have a potential value in cancer therapy." (PMID 26509637, 2016). "HSF1 is involved in promoting metastasis and survival in cancer cells." (PMID 27875990, 2016). "Following secretion of SDF-1 and TGF-β, HSF1 is subsequently activated in neighbouring cancer cells where it drives the expression of genes that facilitate adhesion, migration and extracellular matrix organization, i.e. factors that further promote tumour growth." (PMID 27744329, 2016).
cancer (continued). "Similarly, depletion of HSF1 leads to marked decrease in proliferation and survival in established human cancer of cell lines." (PMID 27713164, 2016). "In cancer, HSF1 controls many genes that may support the transformed phenotype, including genes involved in cell-cycle regulation, signaling, metabolism, adhesion and translation." (PMID 27997575, 2016). "Furthermore, IER5-mediated activation of HSF1 is required for anchorage-independent cell growth of cancer cells." (PMID 26754925, 2016). "Therefore, inhibition of the HSF1-stress pathway represents an exciting new opportunity in cancer treatment." (PMID 27746890, 2016). "Recent findings have highlighted the potential importance of HSF1 activation in cancer." (PMID 26754925, 2016). "This might be particularly important for cancer cells for which it was shown that Hsf1 is a driver of malignancy." (PMID 26785146, 2016). "We observe that depletion of IER5 in cancer cells results in decreased HSF1 activity." (PMID 26754925, 2016). "In addition to systemic control of the cellular stress response, HSF-1 is also a critical factor in other complex human diseases, such as cancer, through transcriptional networks distinct from stress." (PMID 26773049, 2016). "The association of IER5 and HSPA6 expression with cancer progression may be related to the in vitro observation that IER5 and HSF1 are required for the proliferation of cancer cells under stressed conditions." (PMID 26754925, 2016). "Besides its role as a transcription factor in stressed cells, HSF1 is involved in a multitude of physiological processes such as cell metabolism, gametogenesis, aging, insulin signaling, and cancer progression." (PMID 27446966, 2016). "Also, since hsp90 inhibition causes hsp70 induction by HSF1 activation as a compensatory feed-back mechanism, combined inhibition of hsp90 and hsp70, or of hsp90 and HSF1 might be a more effective therapeutic approach for cancer treatment than single HSP targeting alone." (PMID 25759792, 2015). "In cancer HSF1 orchestrates, a wide range of fundamental cellular processes that are not related to heat shock response but are critical for malignant transformation and maintenance, including cell-cycle control, ribosomal biogenesis, protein translation, and inhibition of apoptosis." (PMID 25954247, 2015). "As a result, the activation of HSF1 in CAFs promotes malignancy in adjacent cancer cells." (PMID 26511079, 2015). "Therefore, it is plausible that down-regulation of SIRT1 would prevent 17-AAG-mediated induction of HSF1, Hsp70 and P-gp, and consequently sensitize cancer cells to 17-AAG." (PMID 26416354, 2015). "This HSP and HSF1 inhibition may also contribute to the observed cancer-preventing effects of a flavonoid-rich diet, which includes fruits and vegetables." (PMID 25759792, 2015). "Importantly, cancer-specific HSF1-bound genes (“HSF1 cancer signature”) were found enriched in the biopsies of human breast, colon, and lung tumors and strongly correlated with poor patient outcomes underscoring the critical role of HSF1 in tumorigenesis." (PMID 25954247, 2015). "The implication is that the heat shock pathway and HSF1 responds differentially to evolving cellular conditions and that chronic activation of this pathway may allow cells to adapt to a cancer state." (PMID 26320184, 2015). "The HSF1-dependent chemoresistance of cancer cells could be connected to its interactions with other proteins and/or its impact (direct or indirect) on expression of non-HSPs genes." (PMID 24467529, 2014). "Thus, it has been assumed that HSF1 affects tumor initiation by regulation of HSPs expression, which also have an important role in cancer." (PMID 24467529, 2014).
cancer (continued). "However, the treatment of cancer cells with HSP or proteasome inhibitors results in the HSF1 activation and compensatory induction of HSPs, therefore reducing the antitumor activity of such inhibitors." (PMID 24467529, 2014). "Because this HSF1-driven transcriptional program is strongly associated with metastasis and death in a wide range of cancers, HSF1 could become an effective target for cancer therapeutics." (PMID 24800749, 2014). "For this reason, future studies might benefit by focusing on the identification of new classes of inhibitors against the HSF1 regulated chaperone network in order to help improve the overall clinical outcomes for patients with cancer." (PMID 24800749, 2014). "Indeed, HSF1 is found to be activated in a wide variety of malignant cells, and the pattern of DNA occupancy by HSF1 in such cancer cells is different from that of normal cells exposed to heat shock." (PMID 24800749, 2014). "Further research of the roles of HSF1 in Induction of HSP70/90 high expression in cancer is needed." (PMID 25147790, 2014). "Here, we review the possible function of HSF1 in cancer biology." (PMID 24467529, 2014). "Moreover, our findings raise the interesting possibility that an aptamer that functionally inactivates HSF1 can be used to block human cancer progression." (PMID 24800749, 2014). "HSF1 could be also activated by altered kinase signaling characteristic for cancer cells, which is a probable reason for its high activity found in a broad range of tumors." (PMID 24467529, 2014). "A number of known and previously unknown oncogenes were identified, some of which have already been reported to be associated with cancer, including: ADCY8, ZFAT, BAI1, PTK2, FBXL6, FOXH1, HSF1, and UGT2A1." (PMID 25372838, 2014). "Following this example, we examined whether HSF1 over-expression could rescue cancer cells that express iaRNAHSF1 from undergoing apoptosis." (PMID 24800749, 2014). "The essential role HSF1 in carcinogenesis makes it an attractive target for anti-cancer strategies." (PMID 24467529, 2014). "Because this HSF1 signature is associated with poor patient outcomes in different types of human cancers including those of breast, lung and colon, HSF1 may be a target for general and effective cancer therapeutics." (PMID 24800749, 2014). "Relevant to the case of HSF1, only a small class of naturally occurring molecules have been identified that inhibits molecular chaperones, and of these, only a handful have been tested to sensitize cancer cells to pharmacological treatment." (PMID 24800749, 2014). "Abnormal up-regulation of FOXM1, found in the majority of solid human cancers, correlates with an elevated expression of HSF1, which could directly induce genomic instability." (PMID 24467529, 2014). "For example, Heat shock Factor 1 (HSF1) is involved in survival in several cancer cell lines." (PMID 24576043, 2014). "Cancer stage progression is likely to be correlated with the expression of HSF1, which indicates that HSF1 may be a useful biomarker for HCC prognosis and the development of novel therapeutic strategies for its treatment." (PMID 25199534, 2014). "Thus, HSF1 itself becomes an attractive target of anticancer therapy due to its involvement in different cancer-related processes." (PMID 24467529, 2014). "Potentially therefore rapamycin could prevent the Hsf1 activation that frequently compromises the efficiency of Hsp90 inhibitor cancer drugs." (PMID 24970820, 2014). "Activation of HSF1-dependent stress response, a cytoprotective mechanism, may greatly influence development of an adaptive and protective phenotype in cancer cells subjected to anticancer agents." (PMID 24165036, 2013).
cancer (continued). "The aim of the present study was to determine whether HSF1 could have an effect on the survival of cancer cells treated with chemotherapeutic cytotoxic agents." (PMID 24165036, 2013). "To identify the cancer type which may be useful for the stratification of the combinational treatment, we examined HSF1 expression in TCGA database and found that HSF1 is over-expressed in several tumor types." (PMID 23615731, 2013). "It has been hypothesized that elevated Hsp70 level in cancer cells is a consequence of altered HSF1 transcriptional activity, although Hsp70 may be also expressed regardless of HSF1." (PMID 24362507, 2013). "The mechanisms which underlie the elevated expression of molecular chaperones of the HSPA and HSPD families in cancer are currently unclear but may involve the dysregulation of transcription factor HSF1 first shown to couple stress to HSP transcription." (PMID 24278769, 2013). "However, the functional role of HSF1 in human cancer cell resistance to HSP90 inhibitors and the mechanisms underlying the combination effect of HSF1 knockdown and HSP90 inhibitors are not fully understood." (PMID 23615731, 2013). "In future, developing the potent and selective HSF1 pathway inhibitors might eventually be useful for treating human cancer in combination with HSP90 inhibitor or other agents." (PMID 23615731, 2013). "Inhibition of HSF1 suppresses the progression of a wide spectrum of cancers." (PMID 25969759, 2012). "Similar to the case of the KEAP1/NRF2 pathway, activation of HSF1 commonly occurs in cancer." (PMID 24278719, 2012). "In aggressive cancer cells, HSF1 is expressed at high levels, which could amplify its activity and broaden the spectrum of its targets." (PMID 24212658, 2011). "Indeed, in cancer cells, HSF1 regulates genes involved in core cellular functions including proliferation, survival, migration, protein synthesis, signal transduction, and glucose metabolism, making HSF1 a very attractive target in cancer therapy." (PMID 24212658, 2011). "Moreover, HSF1 seems to participate to the metastatic potential of the cancer cell through cooperation with different metastatic related genes, such as the prometastatic co-repressor gene MTA1." (PMID 24212658, 2011). "HSF1 acts as a major multifaceted enhancer of tumorigenesis by regulating diverse core cellular functions that include proliferation, survival, protein synthesis and glucose metabolism, and therefore, is an attractive potential target in cancer therapy." (PMID 24212658, 2011). "Thus, HSF1 can impair the apoptotic pathway in cancer cells, at least partly, in a HSP independent manner." (PMID 24212658, 2011). "Consistently, proteasome inhibitors, a well-known class of potent anti-cancer agents, up-regulate HSPs synthesis in cancer cells by stimulating hyperphosphorylation and DNA binding of HSF1, and this occurs through enhanced expression and activity of p38MAPK kinase." (PMID 24213118, 2011). "HSF1 inactivation inhibits the progression of a wide spectrum of cancers." (PMID 21978374, 2011). "In addition, quercetin inhibits expression and activity of protein kinases involved in growth and survival of cancer cells, including few critical for HSF1 transcriptional activity and Hsp70 expression." (PMID 24213118, 2011). "It is possible that the core function pathways regulated by HSF1 in normal cells might be massively mobilized in cancer cells, like signal transduction, ribosome biogenesis, translation and glucose metabolism." (PMID 24212658, 2011). "HSF1 is often elevated in human cancer cells compare to normal cells." (PMID 24212658, 2011). "Interestingly, under specific stress pressure, the heat-shock transcription factor 1 (HSF1) was demonstrated to function as a negative regulator of xaf1 expression in various gastroinstestinal cancer tissues and cell lines." (PMID 17376236, 2007). "Thus, HSF1 safeguards the cancer proteome, enabling the oncogenic capacity of mTORC1." (PMID 41835397, 2026).
cancer (continued). "In a different study the authors proposed a mechanism by which HSF1 promotes the growth of pre-malignant cells and HCC by stimulating lipid synthesis and cellular longevity in the presence of carcinogens, with HSF1-deficient mice showing reduced cancer progression." (PMID 40287736, 2025). "In addition to maintaining proteostasis, HSF1 also plays a critical role in cancer progression." (PMID 41028522, 2025). "However, overexpression of HSF1 may promote tumorigenesis, creating a state of “HSF1 addiction” in cancer cells." (PMID 40287736, 2025). "However, the cancer‐associated transcriptional program driven by HSF1 is not limited to HSPs, but includes genes involved in cell proliferation and adhesion, as well as development and metabolism." (PMID 40457168, 2025). "In addition to its role during acute proteotoxic stress, SUMOylation at K298 may also influence HSF1 stability and long-term cellular outcomes such as cancer cell proliferation." (PMID 40617887, 2025). "Notably, the involvement of the HSF1/HSPB1 pathway in ferroptosis in cancer has been established." (PMID 39223962, 2024). "Moreover, HSF1 is crucial for maintaining the cancer stem cell phenotype." (PMID 39682216, 2024). "This SUMOylation-modified HSF1 activity contributes to chemoresistance by supporting mitochondrial function and increasing the expression of mitochondrial chaperones, which may help cancer cells to evade chemotherapy-induced stress." (PMID 39850800, 2024). "Additionally, exploring the impact of HSF1-mediated autophagy on chemoresistance in cancer could reveal new strategies to enhance the therapeutic sensitivity in autophagy-dependent tumors." (PMID 39850800, 2024). "Understanding the key HSF1 interactions promoting cancer progression, along with identifying factors that disrupt these protein complexes, may offer valuable insights for developing innovative therapeutic strategies against cancer." (PMID 39682216, 2024). "Therefore, reducing HSF1 could significantly inhibit the growth of cancer cells and promote their apoptosis." (PMID 38589452, 2024). "Hence, therapeutic targeting of HSF1 or its upstream regulator(s) could be a novel and potent mechanism to impede cancer progression and chemoresistance." (PMID 36622366, 2023). "Hence, the effect of dual inhibition of DYRK2 and HSF1 could indeed be additive and needs to be explored in the context of cancer reduction." (PMID 36622366, 2023). "Furthermore, HSF1 has emerged as a promising target for cancer therapy." (PMID 37958341, 2023). "On the other hand, HSF1 in cancer cells could be induced by CAFs as well." (PMID 37153737, 2023). "In addition, we emphasize new advances with regard to HSF1 inhibitors for cancer drug development." (PMID 37153737, 2023). "Furthermore, HSF1 in cancer cells may be impacted by numerous signaling pathways and oncogenic alterations, resulting in an environment in which HSF1 promotes cancer cell survival and expansion." (PMID 37958341, 2023). "Furthermore, higher expression of HSF1 predicts poor progression-free survival in diverse cancers." (PMID 36622366, 2023). "In recent years, more and more studies on m6A in cancer have reported that β-catenin stimulates m6A modification and subsequent translation of HSF1 mRNA by inhibiting miR455-3p production; thus, targeting HSF1 may be a potential therapeutic strategy to intervene in cancers." (PMID 37002245, 2023). "Therefore, targeting HSF1 may provide a promising strategy for overcoming chemotherapy resistance in cancer treatment." (PMID 37958341, 2023). "Indeed, studies using HSF1-knockout mice showed a strong reduction in cancer incidence, and it is now widely accepted that the heat shock response is, to some extent, elevated in cancer cells." (PMID 36980299, 2023). "Additionally, HSF1 participates in physiological and pathological processes including: differentiation, immune response, multidrug resistance, longevity, neurodegeneration, and cancer." (PMID 35874276, 2022).